KLF4 (KLF transcription factor 4)
Diseases named in the same sentence as KLF4 in open-access papers (continued):
Sharing a sentence is not in itself a finding about the gene and the disease.
cancer (continued). "Loss of expression of KLF4 is associated with cancer progression." (PMID 16919171, 2006). "Given KLF4’s role in regulating glycolytic enzymes and mitochondrial integrity, its isoform-specific metabolic reprogramming may underlie both trained immunity in myeloid cells and the metabolic flexibility of cancer stem cells." (PMID 40552304, 2025). "However, it is important to note that therapeutic manipulation of KLF4 must be approached with caution, as certain isoforms are associated with oncogenic potential, activation of telomerase (hTERT), or reprogramming of cancer stem cells." (PMID 40552304, 2025). "KLF4, also known as krüppel-like factor 4, has been widely investigated as a stemness-associated transcription factor, and was confirmed to induce and maintain the self-renewal and pluripotent capacity of stem cells, as well as implicate in cellular reprogramming and cancer initiation." (PMID 36732504, 2023). "Indeed, limma analysis of differentially expressed genes indicated an increased expression of four genes related to cancer stemness: the pluripotency factor KLF4, the PLAUR gene encoding for the urokinase plasminogen activator surface receptor (uPAR), CD44 and CD166." (PMID 36077264, 2022). "Moreover, we showed that the PTTG1 positive cell population in peripheral areas was characterized as octamer-binding transcription factor 4 (OCT4) and transcription factor Krüppel-like factor 4 (KLF4) positive, proteins associated with cancer stem cell self-renewal and invasiveness." (PMID 33430117, 2021). "However, its role in cancer has not been defined conclusively, as it also has been identified as an oncogene in some tissue-specific cancers; for example, KLF4 has been identified as an oncogene and linked increased expression in epithelial carcinomas of the oral cavity." (PMID 31040909, 2019). "The role of KLF4 in maintaining genetic stability is further substantiated by the ability of Klf4 to suppress micronuclei formation in Klf4−/− cells as micronuclei is considered a biomarker of chromosomal damage, genome instability, and eventually of cancer risk." (PMID 23919723, 2013). "However, alternative mechanisms for KLF4 transcriptional inactivation may occur in other KLF4 deficient cancers that don’t exhibit genetic loss and promoter methylation." (PMID 22937066, 2012). "This functional plasticity underscores the importance of considering the cellular and environmental background when interpreting KLF4's role in cancer." (PMID 41532367, 2026). "The function of KLF4 in tumorigenesis is multifaceted, affecting apoptosis, proliferation, differentiation, and invasion of cancer cells." (PMID 41532367, 2026). "Evidence indicates that the role of KLF4 in cancer cells is dualistic, determined by the cancer type or subtype and the specific molecular regulation within signaling pathways." (PMID 41532367, 2026). "Future progress hinges on deeper mechanistic investigations and rigorous clinical validation to translate KLF4‐targeted strategies into effective cancer therapies." (PMID 41532367, 2026). "A comprehensive elucidation of these mechanisms is paramount for the rational design of effective KLF4‐targeted cancer therapeutics." (PMID 41532367, 2026). "Collectively, KLF4 serves as a central node in both innate and adaptive immunity in cancer settings." (PMID 41532367, 2026). "In terms of cancer cell stemness, MIF inhibition in MASLD led to a reduction in CD44+ or ALDH+ or CD44+/KLF4+ cancer cells." (PMID 41545340, 2026). "Although KLF4 has been extensively studied in tumors, its potential clinical value in cancer diagnosis and prognosis has yet to be fully established." (PMID 41532367, 2026). "The communication between KLF4 and cancer cells involves the regulation of diverse genes and biological factors by directly binding to their gene promoters or the downstream effectors." (PMID 41532367, 2026).
cancer (continued). "Krüppel‐like factor 4 (KLF4) is a zinc finger transcription factor that plays context‐dependent roles in cancer." (PMID 41532367, 2026). "In cancer cells, KLF4 has been shown to regulate expression of metabolic genes, including monocarboxylate transporters." (PMID 40486046, 2025). "Initially, KLF4 expression was examined across different cancer types using TCGA datasets with the TIMER2 server." (PMID 40299916, 2025). "Despite significant advances in KLF4 regulatory mechanisms in tumorigenesis, research on KLF4’s role within the immune system and its relationship to cancer remains limited." (PMID 39995670, 2025). "The system also enriched cancer stem-like properties, with higher expression of stemness-associated genes (CD24, CD44, CD133, ALDHA1, CXCR4, Sox2, Oct4, Nanog, and KLF4) and expansion of CSC populations expressing (CD44, CD90, CD117, EpCAM, and CK19)." (PMID 41149589, 2025). "Research on the oncogenic role of KLF4 has mainly focused on overexpression in established cell lines, with limited assessment in mouse models of cancer, especially concerning blood malignancies." (PMID 40589762, 2025). "We believe that the findings presented herein will further clarify the potential role of KLF4 as a prognostic marker and its molecular mechanism in human cancers." (PMID 40299916, 2025). "A recent study evaluated the effect of Orlistat (a drug normally used to treat obesity) on the gene expression of OCT4, NANOG, SOX2, and KLF4 in the CRC cancer cell line SW40." (PMID 40867564, 2025). "Four other genes related to cancer stem cells (CSCs) have also been identified in the CRC in dormant cells: pluripotency factor KLF4, AXIN2, LGR5, and BMI1." (PMID 40867564, 2025). "Sox2, c-Myc, Klf4, and Oct4 are four core stemness factors that play pivotal roles in maintaining cancer cell stemness." (PMID 40332113, 2025). "KLF4 also contributes to cell fate reprogramming and stem cell self-renewal and is considered essential to maintaining cancer stem cells." (PMID 40299916, 2025). "In certain cancers, such as KIRC and LUAD, KLF4 expression is associated with opposing prognostic outcomes." (PMID 40299916, 2025). "These questions warrant deeper exploration to uncover KLF4’s potential as a pivotal molecular target in cancer immunotherapy." (PMID 39995670, 2025). "As research advances, uncovering additional players in the regulatory network and deciphering the crosstalk with signaling pathways will refine our comprehension of KLF4's role in both embryogenesis and cancer biology." (PMID 40034124, 2025). "It is interesting to note that a number of studies support both a pro- and anti-tumorigenic role for KLF4 in cancer cells." (PMID 41155497, 2025). "Stemness of cancer stem cells (CSCs) is associated with expression of the Yamanaka OCT4, SOX2, KLF4 and MYC (OSKM) pluripotency factors that confer lineage plasticity and dedifferentiation." (PMID 40764753, 2025). "We present previously undocumented evidence demonstrating that Nrf2 promotes the expression of the stemness factor KLF4 through the coordinated regulation of enhancers and KLF4 itself, further reinforcing Nrf2's pro‐carcinogenic role in cancer cells and CSCs." (PMID 40755294, 2025). "In colon cancer, KLF4 reduces autophagy in cancer cells by inhibiting RAB26 expression while promoting apoptosis and enhancing response to 5-fluorouracil (5-FU)." (PMID 39995670, 2025). "Among these, there were known regulators such as HOXB2 and KLF4 in Cancer LumA, as well as HMGA1 in Cancer Basal." (PMID 40397381, 2025). "This regulatory mechanism is crucial in both inflammatory diseases and cancer progression, with KLF4 playing a significant role in regulating macrophage pro-inflammatory responses, potentially acting as a key target in the TGF-β1/Smad3 signaling pathway." (PMID 39995670, 2025).
cancer (continued). "In summary, drugs targeting KLF4 are gradually being discovered for their potential to impact malignant tumors, but further mechanistic studies and clinical validation are necessary." (PMID 39995670, 2025). "Regarding genetic instability, the genes SOX2, OCT3/4, c-MYC, and KLF4—commonly used for reprogramming somatic cells to iPSCs—are often expressed at higher levels in various cancer cells and are involved in the development and progression of several cancers." (PMID 40541178, 2025). "This study also explored the prognostic impact of CCND2 and KLF4 expression on various cancer types." (PMID 40487928, 2025). "Understanding the Ub-mediated regulation of KLF4 in CSCs not only sheds light on the delicate equilibrium between self-renewal and differentiation but also unveils potential therapeutic targets for cancer treatment." (PMID 40034124, 2025). "Most research on KLF4 in cancer centers compares its expression in patient samples with that in healthy individuals." (PMID 40589762, 2025). "KLF4 has also been shown to function in the re-activation of CD8 T cells in the immune response against cancer." (PMID 40299916, 2025). "miR-484 directly targeted Krüppel-like factor 4 (KLF4), a critical regulator of transcription factors necessary for cancer stem cell (CSC) development." (PMID 40190354, 2025). "In conclusion, the genetic alterations, dysregulated RNA expression, and prognostic implications of KLF4 in malignancies underscore its significance in cancer biology." (PMID 40299916, 2025). "Future investigations should focus on elucidating the functional roles and regulatory mechanisms of KLF4 to further assess its potential as a therapeutic target and predictive biomarker in cancer management." (PMID 40299916, 2025). "Among the overlapping upregulating genes are G6PD and KLF4, known to be related to cisplatin resistance and upregulated in lung and other cancers." (PMID 41469472, 2025). "Several studies have reported that known compounds exert antitumor effects by acting on KLF4 in diverse types of cancer." (PMID 39995670, 2025). "The RNA-binding protein MEX3A sustains cancer cells in an undifferentiated and proliferative state, enhancing radiotherapy resistance by suppressing KLF4 expression and activating the WNT signaling pathway." (PMID 39995670, 2025). "The role of KLF4 in major cancers, a summary of the top ten cancers by incidence (based on the latest 2024 SEER database report)." (PMID 39995670, 2025). "In this study, a pan-cancer analysis was conducted to investigate the potential impact of KLF4 aberration in human malignant tumors." (PMID 40299916, 2025). "Native TRX, on the other hand, increased KLF4 in both normal and cancer cells and also supported their proliferation." (PMID 40932638, 2025). "Cancer stemness is recognized by the presence of stemness-related markers in human cancers such as Oct4, Sox2, Klf4, c-Myc, Sall4, and Nanog." (PMID 40076435, 2025). "Focusing here on SOX2 and KLF4, which confer stemness in cancer, we found that, in contrast to MUC1-C, EBNA1 suppresses their expression." (PMID 40764753, 2025). "We confirmed that the expression levels of AXL and CYR61, target proteins of YAP/TAZ signaling, as well as the expression levels of c-MYC and KLF4, factors representing the cancer cell undifferentiated state, were similarly decreased." (PMID 39604563, 2025). "Genetic alterations in KLF4 were examined using the cBio portal, with 10,953 samples out of 10,967 samples from TCGA database for different cancers examined." (PMID 40299916, 2025).
cancer (continued). "Regarding cancer stemness, Ad-VP3 significantly impaired sphere-forming capacity and reduced the expression of stemness-associated proteins ALDH1A1, KLF4, and Sox2 in a time-dependent manner at 48 h and 72 h post-infection." (PMID 41472305, 2025). "The pan-cancer analysis of KLF4 revealed that the highest alteration frequencies are present in UCEC (3.4%) and BLCA (2.92%)." (PMID 40299916, 2025). "RPL10 UFMylation enhances cell proliferation and promoted cancer cell stemness via upregulation of KLF4." (PMID 39247188, 2024). "KLF4 transcription factor, a critical regulator of cell biology process, including cell cycles, apoptosis, cancer metastasis and cancer stem cells." (PMID 39695175, 2024). "The results demonstrated that reactivated miR-25-3p by the mimics abrogated the MACC1-mediated elevation of KLF4 at the mRNA and protein levels in two cancer cell lines." (PMID 39695175, 2024). "Although the relationship between EphA2 and YAP is supported by our and others’ results, knowledge of the connection between YAP and KLF4 is limited in cancer." (PMID 38916835, 2024). "The IPA summary of contralateral PTE+ cortical astrocytes shows predicted activation of serine peptidase inhibitor Kazal type 1 (SPINK1) general cancer pathway, as well as IL-15 production, KLF4, SOX4 and migration of phagocytes/myeloid cells." (PMID 38600221, 2024). "Krüppel-like factor 4 (KLF4) is a common downregulated TF in cancer that would inhibit IFITM3 and SOX4 expression." (PMID 39228892, 2024). "RPL10 UFMylation enhances cell proliferation and promoted cancer cell stemness, primarily through upregulated expression of KLF4 (kruppel-like transcription factor 4)." (PMID 39247188, 2024). "Glioblastoma cell lines T731 and T653 were reprogrammed with Oct4, Sox2, and Klf4 to derive induced pluripotent cancer cells, and the use of a small molecule, PD98059, was shown to increase reprogramming efficiency." (PMID 38247819, 2024). "In this regard, mechanistically, Klf4 has been previously shown to regulate the levels of p21 in a cancer context dependent manner." (PMID 39587064, 2024). "The transcription factor KLF4 has been reported to promote cancer cell stemness in various types of cancers." (PMID 38308285, 2024). "Oct4, Sox2, c-Myc and Klf4 had been identified as cancer stem cell (CSCs) markers, playing a key role in the reprogramming of somatic differentiated cells into induced pluripotent stem cells (iPSCs)." (PMID 38822350, 2024). "Collectively, these evidences demonstrate how the chromatin conformational changes mediated by histone methylation/demethylation represent a mechanism adopted by cancer cells to downregulate KLF4." (PMID 39135777, 2024). "It is reported that MDSCs activate STAT3 signaling by stimulating the expression of colony stimulating factor 2 (CSF2) in epithelial ovarian cancer, thereby enhancing the transcription of SOX2, NANOG, OCT4a, C-MYC, and KLF4, as well as cancer stemness." (PMID 38561775, 2024). "The epigenetic regulation of the zinc-finger TF KLF4 plays a relevant role in several types of cancers, as demonstrated by the recent literature." (PMID 39135777, 2024). "KLF4 is a transcription factor that acts as a tumour suppressor in some cancers, and as an oncogene in other cancers." (PMID 38497605, 2024). "Duct-like organoid colonies with extensive stroma mimicking the topology of PDAC, SOX2 and KLF4 transcriptional factors, cancer stem cells’ functionality (CD133 +/CXCR4+ PDAC cells)." (PMID 38791452, 2024). "Krϋppel-like factor 4 (KLF4) is a transcription factor with roles in stemness, embryonic development, and cancer, acting either as an oncogene or tumor suppressor." (PMID 38539439, 2024). "In cancer stem cells, Myc, Nanog, Oct4, KLF4 and Sox2 are established to be the leading factors for stemness." (PMID 38794128, 2024).
cancer (continued). "In cancer cells, KLF4 is suppressed, and YAP promotes snail family transcriptional repressor 2 (SNAI2) expression, which is involved in downregulating KLF4 expression." (PMID 39684613, 2024). "Oral squamous cell carcinoma (OSCC) is another cancer where the epigenetic regulation of KLF4 has been demonstrated." (PMID 39135777, 2024). "The methylation status of HS3ST2 and KLF4 was detected in cancerous, hyperplastic and normal endometrial tissues, and multinomial logistic regression analysis showed that HS3ST2 and KLF4 were predictors of endometrial hyperplasia and carcinoma." (PMID 39902129, 2024). "miR-144, which has been shown to increase stemness in CRC, regulates KLF4 and contributes to the maintenance of cancer stem cells in CRC by increasing their proliferation and invasion." (PMID 37173904, 2023). "Kenpaullone targets KLF4 and has been shown in animal studies to inhibit the proliferation and migration of cancer cells." (PMID 36761967, 2023). "Several studies reveal that cancer stem cell subpopulations marked by c-MET or CD24/CD44/EpCAM expression are characterized by high expression of reprogramming factors such as KLF4." (PMID 37239940, 2023). "The following discussion focuses on the specific cancer-regulating roles of KLF4 in ten common cancers." (PMID 37031197, 2023). "Our findings demonstrate that EGR1 plays a crucial role in facilitating VM in aggressive cancer cells by regulating KLF4 expression." (PMID 37762678, 2023). "The results showed that the 3’-UTR of human KLF4, a cancer stemness-related gene, was predicted to contain a binding site for the seed sequence of miR-7-5p." (PMID 36732504, 2023). "For example, genes encoding chromatin regulators involved in pluripotency, OCT4, SOX2, KLF4, NANOG, and LIN28, are rarely mutated, but frequently overexpressed in cancer, thus rendering pharmacologic interventions challenging." (PMID 36919699, 2023). "MYC is one of the well-characterized transcription factors, including OCT4, SOX2, NANOG, KLF4, in cancer stem cell establishment, maintenance, and functions." (PMID 36941257, 2023). "Mechanistically, KLF4 is enriched in the demethylated p21 promoter and increases its expression, thus blocking the cell cycle of cancer cells in the G1 phase." (PMID 36761967, 2023). "In the context of PDAC, KLF4 levels are increased in cancer stem cells alongside three other Yamanaka factors: OCT4, NANOG, and SOX2." (PMID 37239940, 2023). "The pluripotency markers NANOG and the Yamanaka factors OCT4, SOX2, KLF4 and c-MYC have previously been shown to be linked with enhanced cancer stem cell properties in cancer cells." (PMID 37950151, 2023). "Klf4 is known to regulate cell adhesion in many tissues, and Klf4 inhibition can alter cell migration in specific cancers." (PMID 37180153, 2023). "Klf4 overexpression was found in squamous cells and other cancer-forming processes, and c-Myc was the main oncogenic factor related to tumorigenesis and glycolysis as well as being linked to Wnt/β-catenin signaling in lung cancer." (PMID 37761837, 2023). "As the most well‐known factor of the KLF family, the function of KLF4 in cancer has been extensively studied." (PMID 37400979, 2023). "MUC5AC stimulates signaling through integrin avb5, pSrc (Y416), and pSTAT3 (Y705), which upregulates KLF4 and increases the tumorigenic propensity of cancer stem cells." (PMID 37239940, 2023). "From the perspective of interpreting VM as the differentiation of cancer stem cells into endothelial-like cells, it can be inferred that EGR1 maintains the stemness and endothelial differentiation capacity of cancer stem cells by regulating KLF4." (PMID 37762678, 2023).